Y_RNA (Y RNA )
Gene: Miscellaneous RNA gene on chromosome X (118,569,405 to 118,569,515, reverse strand). Ensembl gene ENSG00000206862.
Homologues: Orthologues: chimpanzee Y_RNA (99% identical), macaque Y_RNA (96% identical), guinea pig Y_RNA (89% identical), guinea pig Y_RNA (85% identical). Paralogues in human: RNY1 (87% identical), Y_RNA (86% identical), RNY1P11 (86% identical), Y_RNA (85% identical), Y_RNA (84% identical), RNY1P5 (83% identical), Y_RNA (83% identical), RNY1P10 (82% identical), RNY1P8 (82% identical), Y_RNA (82% identical), Y_RNA (81% identical), RNY1P7 (80% identical), and 97 more.